TFAP2B (transcription factor AP-2 beta)
Diseases named in the same sentence as TFAP2B in open-access papers (continued):
Sharing a sentence is not in itself a finding about the gene and the disease.
lung adenocarcinoma (5 papers, 2014 to 2024). A carcinoma that arises from the lung and is characterized by the presence of malignant glandular epithelial cells. "TFAP2B is also highly expressed in other tumours, e.g. lung adenocarcinomas and is associated with a poor prognosis for patients." (PMID 31493794, 2019). "Here, we investigated the regulatory effects of TFAP2B on lung adenocarcinomas growth and identified the underlying mechanisms of actions in non-small cell lung cancer (NSCLC) cells." (PMID 24766673, 2014). "We also analyzed lung adenocarcinoma specimens in a tissue array and evaluated the prognostic predicting value of TFAP2B in lung adenocarcinomas." (PMID 24766673, 2014). "Strong TFAP2B expression showed a positive correlation with the poor prognoses of patients with lung adenocarcinomas (P < 0.001)." (PMID 24766673, 2014). "The clinicopathologic data from our tissue array showed that patients with lung adenocarcinomas, which highly expressed the TFAP2B protein, had shorter survival periods than patients with TFAP2B-weakly positive/negative tumors." (PMID 24766673, 2014). "Our study also demonstrated that high TFAP2B expression independently predicted a worse overall survival in patients with lung adenocarcinomas." (PMID 24766673, 2014). "We also immunohistochemically detected the expression of the TFAP2B protein in lung adenocarcinoma and adjacent area." (PMID 24766673, 2014). "We evaluated the expression of TFAP2B using TMA-containing tumors from 147 patients with lung adenocarcinoma with full clinical annotation to assess the biological and clinicopathologic significance." (PMID 24766673, 2014). "We also analyzed the prognostic predicting value of TFAP2B in lung adenocarcinomas." (PMID 24766673, 2014).
type 2 diabetes (5 papers, 2011 to 2019). "The TFAP2B gene has been associated with type 2 diabetes, and was recently found to be related to BMI and waist circumference." (PMID 22952648, 2012). "Studies have shown an association between TFAP2B and type 2 diabetes, and over-expression of TFAP2B in adipocytes leads to IR and accumulation of triglycerides inside the adipocytes." (PMID 21674055, 2011).
alveolar rhabdomyosarcoma (3 papers, 2009 to 2021). A rapidly growing malignant mesenchymal neoplasm. "TFAP2B is a diagnostic marker for alveolar rhabdomyosarcoma (aRMS) and has been reported to mediate anti-apoptotic signals in aRMS." (PMID 34359596, 2021).
central obesity (3 papers, 2011 to 2023). "Also, analyses of rs987237 in TFAP2B showed borderline association with central obesity among women." (PMID 21674055, 2011). "In conclusion, we found that several of the central obesity-associated variants in LYPLAL1, NRXN3, MSRA, and TFAP2B associated with metabolic and anthropometric traits among adult Danes." (PMID 21674055, 2011). "In this study we found several associations with quantitative metabolic and anthropometric traits for the central obesity-associated variants in LYPLAL1, NRXN3, MSRA, and TFAP2B." (PMID 21674055, 2011). "The aim of the present study was to investigate central obesity-associated variants in LYPLAL1, NRXN3, MSRA, and TFAP2B for associations with quantitative metabolic traits in a population-based sample of 6,038 adult Danes (The Inter99 study sample)." (PMID 21674055, 2011). "We demonstrate that several of the central obesity-associated variants in LYPLAL1, NRXN3, MSRA, and TFAP2B associate with metabolic and anthropometric traits in Danish adults." (PMID 21674055, 2011). "Reduced expression of TFAP2B may have a protective effect against diminished insulin sensitivity and central obesity-related complications such as T2DM and coronary artery disease." (PMID 36627697, 2023). "The MSRA rs545854 and TFAP2B rs987237 showed nominal associations with central obesity; however, no underlying metabolic phenotypes became obvious, when investigating quantitative metabolic traits." (PMID 21674055, 2011).
glaucoma (3 papers, 2016 to 2022). Increased pressure in the eyeball due to obstruction of the outflow of aqueous humor. "For example, we show a remarkable long-range interaction leading to identification of the target gene TFAP2B for glaucoma-associated variant rs72904286 at the TFAP2B/PKHD1 locus." (PMID 36207300, 2022). "The observation strongly supports the idea that the significant down-regulation of Tfap2b gene expression observed in our transgenic animals is causally related to the appearance of glaucoma." (PMID 28894266, 2017). "Down-regulation of AP-2β expression is likely to be responsible for the pathologic phenotype, as conditional deletion of the Tfap2b gene in the neural crest has recently been shown to cause defective development of the eye anterior segment and early-onset glaucoma." (PMID 28894266, 2017). "However, it was not possible to examine later defects in the Tfap2b-null mice, including features of glaucoma, due to perinatal lethality." (PMID 27483349, 2016).
glioblastoma (3 papers, 2020 to 2025). The most malignant astrocytic tumor (WHO grade IV). "Gene expression analysis of glioma and glioblastoma cells revealed that Meis2 was one of the differentially expressed genes and it could be a prognostic biomarker for glioma and glioblastoma development, in addition to with other genes, including Meox2, Pitx2, Nr2e1, and Tfap2B." (PMID 33402862, 2020).
Insulin resistance (3 papers, 2015 to 2025). Increased resistance towards insulin, that is, diminished effectiveness of insulin in reducing blood glucose levels. "It has been shown that overexpression of TFAP2B results in lipid accumulation by enhancing glucose transport and inducing insulin resistance and decreases the secretion of adiponectine and leptin in human adypocites." (PMID 25890290, 2015).
metabolic syndrome (3 papers, 2011 to 2023). A cluster of metabolic risk factors for CARDIOVASCULAR DISEASES and TYPE 2 DIABETES MELLITUS. "Another study, comprising 81 individuals suggested that TFAP2B might be a novel candidate gene for development of the metabolic syndrome, as it was shown to regulate the expression of various adipokines." (PMID 21674055, 2011). "It appeared that the effect sizes of most T2D-associated SNPs, with the exception of a few outliers (e.g., FTO, MC4R, POCS, and TFAP2B), were not affected by BMI or dyslipidemia." (PMID 30054458, 2018).
non-small cell lung carcinoma (3 papers, 2014 to 2023). A group of at least three distinct histological types of lung cancer, including non-small cell squamous cell carcinoma, adenocarcinoma, and large cell carcinoma. "TFAP2B has been proven to promote the progression of non-small cell lung cancer and thyroid cancer through VEGF/PEDF and COX-2 signaling pathway." (PMID 37859819, 2023). "For example, TFAP2A expression was elevated in nasopharyngeal carcinoma, which promoted nasopharyngeal carcinoma proliferation and growth via inducing cyclooxygenase-2 expression; in addition, TFAP2B was reported to be overexpressed in non-small cell lung cancer (NSCLC) tissues and cell lines." (PMID 29439714, 2018).
thyroid cancer (3 papers, 2019 to 2023). "However, high TFAP2B/COX-2 expression levels were associated with multifocal thyroid cancer and N stage (P < 0.05)." (PMID 31113934, 2019). "In this study, we detected the function of TFAP2B in the processes of thyroid cancer cell migration and invasion using wound-healing and transwell-invasion assays." (PMID 31113934, 2019). "We established TFAP2B knockdown and overexpression stable thyroid cancer cell lines to further investigate the function of TFAP2B in thyroid cancer cell growth and proliferation in vitro and in vivo." (PMID 31113934, 2019). "A thyroid cancer xenograft model was used to confirm thyroid tumorigenesis with TFAP2B/COX-2 expression." (PMID 31113934, 2019). "We found that thyroid cancer cell viability and colony formation were inhibited in the knockdown TFAP2B cell line." (PMID 31113934, 2019). "Among the cell lines examined, the expression of TFAP2B/COX-2 was obviously higher in thyroid cancer cell lines than in normal human thyroid cell lines." (PMID 31113934, 2019). "We also analyzed thyroid cancer specimens in a tissue array and evaluated the prognostic predictive value of TFAP2B/COX-2 in thyroid cancer by combining the information with the clinical data." (PMID 31113934, 2019). "In summary, these results suggest that TFAP2B regulates thyroid cancer development and progression via COX-2-mediated downstream signaling pathways." (PMID 31113934, 2019). "Afterward, MTS, colony formation, cell-apoptosis assay, transwell-invasion and scratch assays were performed to examine the proliferation, apoptosis, invasion, and migration of thyroid cancer cells with TFAP2B knocked down or overexpressed." (PMID 31113934, 2019). "The mouse xenograft experiment was performed to study in vivo the proliferation of thyroid cancer cells with TFAP2B knocked down or overexpressed." (PMID 31113934, 2019). "TFAP2B mediated thyroid cancer cell proliferation, apoptosis, invasion, and migration via the COX-2 signaling pathway in vitro and in vivo." (PMID 31113934, 2019). "TFAP2B bound to the promoter of COX-2 to activate its expression, indicating that TFAP2B is a critical regulatory molecule in the COX-2 signaling pathway that promoted tumor progression in thyroid cancer." (PMID 31113934, 2019). "We examined the expression of TFAP2B/COX-2 at the protein level in thyroid cancer cell lines and tumor tissues." (PMID 31113934, 2019). "High levels of TFAP2B were bound to the COX-2 promoter probe in thyroid cancer cells (K2, TPC-1, KTC-1, and BCPAP)." (PMID 31113934, 2019). "The clinicopathologic data from our tissue array showed that high expression of TFAP2B/COX-2 is relevant to more advanced T classification and N classification, and more likely to be associated with multifocal carcinoma in thyroid cancer." (PMID 31113934, 2019). "Western blot and immunohistochemistry showed that TFAP2B/COX-2 was highly expressed in thyroid cancer, and high TFAP2B and COX-2 expression was associated with aggressive clinicopathological features in thyroid cancer." (PMID 31113934, 2019). "Our study showed that sex, age, thyroid cancer-assisted Hashimoto’s thyroiditis (HT), and recurrence did not have any statistically significant difference according to TFAP2B/COX-2 expression levels (P > 0.05)." (PMID 31113934, 2019). "Meanwhile, overexpression of TFAP2B significantly promoted thyroid cancer cell viability and colony formation." (PMID 31113934, 2019). "We knocked down and overexpressed TFAP2B to evaluate the effect of TFAP2B on thyroid cancer cell growth, metastasis, and invasion, and we further elucidated the underlying molecular mechanisms involved in modulating COX-2." (PMID 31113934, 2019). "TFAP2B can specifically bind to the COX-2 promoter in thyroid cancer cells." (PMID 31113934, 2019).
thyroid cancer (continued). "To confirm this prediction in thyroid cancer, we investigated the association between thyroid tumorigenesis and TFAP2B/COX-2 expression and determined whether TFAP2B modulated COX-2 to promote thyroid cancer progression." (PMID 31113934, 2019). "We clearly substantiated the biological role of TFAP2B/COX-2 in thyroid cancer and suggest that it could serve as a novel therapeutic and diagnostic target for thyroid cancer." (PMID 31113934, 2019). "In conclusion, in the thyroid cancer cell line, COX-2 signaling can be modulated by TFAP2B, and TFAP2B drives tumor development in thyroid cancer as an oncogene." (PMID 31113934, 2019). "TFAP2B binds to the promoter of COX-2 to activate its expression, revealing that TFAP2B is a ponderable regulatory molecule in the COX-2 signaling pathway, affecting tumor progression in thyroid cancer and is a potentially effective target for thyroid cancer diagnosis and therapy." (PMID 31113934, 2019).
depression (2 papers, 2017 to 2025). "TFAP2B gene variants have previously been related to different personality dimensions in women, namely anxiety, psychasthenia, guilt, depression, impulsiveness, indirect aggression or addictive behavior; features that are often present in women with ED." (PMID 28948079, 2017).
mediastinal tumours (2 papers, 2024 to 2025). "HN-PG and the suspected non-chromaffin mediastinal tumours had low expression of the chromaffin cell marker CARTPT24, neural transcriptional regulators (TFAP2B, TOX3, GATA3, POU4F, NEUROG2, PAX2), HOX genes (HOXA1-10, HOXB4, HOXB6-9, HOXC4-HOXC13), and the long non-coding RNA HOTAIR." (PMID 40097403, 2025). "HN-PG and the suspected non-chromaffin mediastinal tumours had low expression of the chromaffin cell marker CARTP24, neural transcriptional regulators (TFAP2B, TOX3, GATA3, POU4F, NEUROG2, PAX2), HOX genes (HOXA1–10, HOXB4, HOXB6–9, HOXC4-HOXC13), and the long non-coding RNA HOTAIR." (PMID 38978571, 2024).
papillary carcinoma of the thyroid (2 papers, 2019 to 2020). "We found a positive association between TFAP2B and AP-1 expression in papillary thyroid carcinoma patients, but due to a few studies which assessed their expression, we assessed the expression of another biomarker which is JAZF1." (PMID 32856873, 2020). "TFAP2B expression in papillary thyroid cancer tissues is positively associated with a high incidence of disease progression, recurrence of the tumor (p=0.002), unfavourable disease-free survival rate (p=0.003)." (PMID 32856873, 2020). "In our study, we clarified that TFAP2B higher expression increased the growth of papillary thyroid cancer." (PMID 32856873, 2020). "In our study, TFAP2B expression was high in papillary thyroid cancer cell lines compared with normal cells and in tumor tissues compared with tissues adjacent to tumors." (PMID 31113934, 2019). "In conclusion, we demonstrated that expression levels of TFAP2B and AP-1 protein were increased while the expression levels of JAZF1 were decreased in papillary thyroid carcinoma in comparison with non-neoplastic thyroid tissues using immunohistochemistry." (PMID 32856873, 2020).
adrenocortical carcinoma (1 paper, 2025). "Further species-level verification and prognostic importance nominated three promising pairs: Paraburkholderia fungorum–TFAP2E in adrenocortical carcinoma (ACC), Actinomyces oris–TFAP2E in diffuse large B-cell lymphoma (DLBC), and Cutibacterium granulosum–TFAP2B in stomach adenocarcinoma (STAD)." (PMID 41373739, 2025).
Alagille syndrome (1 paper, 2022). "Several syndromes with associated mouse models such as Char syndrome (TFAP2B) and Alagille syndrome (JAG1) have well‐known associations with PDA." (PMID 34350653, 2022).
angle-closure glaucoma (1 paper, 2017). The sudden increase of intraocular pressure, resulting in pain and an abrupt decrease in visual acuity. "With respect to this, it is worth noticing that our data indicate that full suppression of Tfap2b gene expression is not necessary to cause a deficit in the development of the anterior segment of the eye which results in angle-closure glaucoma." (PMID 28894266, 2017).
anorexia nervosa (1 paper, 2017). A disorder most often seen in adolescent females characterized by a refusal to maintain a minimally normal body weight, an intense fear of gaining weight, a disturbance in body image, and, in postmenarcheal females, the development of amenorrhea. "Haplotype *6 in KCTD15 was more frequent in controls (OR = 0.40 [0.20–0.80], p = .009 for anorexia nervosa), while haplotype *4 in TFAP2B affected all three scales of the SCL‐90R inventory in BN patients (p ≤ .01)." (PMID 28948079, 2017). "According to this background, we hypothesized in the present work that TFAP2B and KCTD15 variants, either isolated or in combination, may influence personality dimensions in anorexia nervosa (AN) or bulimia nervosa (BN) patients." (PMID 28948079, 2017).
autosomal recessive polycystic kidney disease (1 paper, 2022). An inherited disorder characterized by the development of cysts affecting the collecting ducts. "Mice lacking functional Tfap2b gene die in the perinatal or neonatal period with cystic dilatation of the kidney distal tubules and collecting ducts, a phenotype resembling autosomal recessive polycystic kidney disease (ARPKD)." (PMID 36710876, 2022).
Barrett esophagus (1 paper, 2019). Esophageal lesion lined with columnar metaplastic epithelium which is flat or villiform. "Expression of LGALS4 and TFAP2B show higher or lower expression in Barrett's esophagus, respectively, and this level of expression is maintained in EAC, mirroring the loci accessibility patterns." (PMID 30962179, 2019). "Genome Browser tracks of the LGALS4 (gained accessible region) and TFAP2B (lost accessible region) loci illustrate the “maintenance” of chromatin accessibility states in EAC compared to Barrett's esophagus." (PMID 30962179, 2019).
bladder cancer (1 paper, 2023). "A whole genome methylation sequencing results of bladder cancer showed that the methylation level of TFAP2B in high-level bladder cancer was significantly higher 17, which is consistent with our finding." (PMID 37859819, 2023). "We analyzed the relationship between TFAP2 family proteins and the clinical stage of bladder cancer patients, and found that TFAP2C protein was positively correlated with the worse clinical stage of patients, while TFAP2B showed the opposite trend." (PMID 37859819, 2023). "Immunohistochemical results from HPA database showed that the expression of TFAP2A, TFAP2B and TFAP2C in clinical samples of bladder cancer patients was higher than that in normal tissues." (PMID 37859819, 2023). "The trend of survival curve of TFAP2A, TFAP2B and TFAP2C in bladder cancer was basically consistent with that of GEPIA." (PMID 37859819, 2023). "The survival analysis of TFAP2 family genes by GEPIA database showed that TFAP2A, TFAP2B and TFAP2C were significantly related to the survival and prognosis of bladder cancer patients." (PMID 37859819, 2023). "We used SMART database to analyze the methylation of different TFAP2 family in patients with BLCA, and found that the methylation of TFAP2A, TFAP2B, TFAP2D and TFAP2E in bladder cancer tissues was significantly higher than that in adjacent tissues, while TFAP2C showed the opposite trend." (PMID 37859819, 2023). "But our data from FFPE sample showed that TFAP2B is related to the earlier T stage of bladder cancer, but not to lymph node metastasis, which suggests that TFAP2B may be an inhibitor of bladder cancer growth." (PMID 37859819, 2023).
cataract (1 paper, 2016). Partial or complete opacity of the crystalline lens of one or both eyes that decreases visual acuity and eventually results in blindness. "A similar mechanism could account for the observed corneal lenticular adhesions and subsequent subcapsular cataracts that occur in this Tfap2b model." (PMID 27483349, 2016).
chronic kidney disease (1 paper, 2024). Impairment of the renal function secondary to chronic kidney damage persisting for three or more months. "Through analyzing the GEO database, we found that TFAP2B was significantly upregulated in kidney biopsy tissues from patients with chronic kidney disease." (PMID 38710691, 2024). "The results revealed that the expression of TFAP2B, a transcript factor, was significantly upregulated in kidney biopsy tissues from patients with chronic kidney disease compared to healthy individuals." (PMID 38710691, 2024).
congestive heart failure (1 paper, 2011). Failure of the heart to pump a sufficient amount of blood to meet the needs of the body tissues, resulting in tissue congestion and edema. "As Tfap2b was not expressed in lungs, this phenotype was most likely secondary to the patent DA and was a sign of congestive heart failure, which might be a further cause for the early lethality of Tfap2b mutant mice." (PMID 21829553, 2011).